CTSB (cathepsin B)
Diseases named in the same sentence as CTSB in open-access papers (continued):
Sharing a sentence is not in itself a finding about the gene and the disease.
female infertility (1 paper, 2021). Diminished or absent ability of a female to achieve conception. "Hence, CTSB could be a potential prognostic agent for female infertility." (PMID 34769258, 2021).
Fulminant hepatic failure (1 paper, 2025). Hepatic failure refers to the inability of the liver to perform its normal synthetic and metabolic functions, which can result in coagulopathy and alteration in the mental status of a previously healthy individual. "Previous studies demonstrated that cathepsin B contributes to fulminant hepatic failure and acetaminophen hepatotoxicity via hepatocyte apoptosis." (PMID 41323645, 2025).
gallstones (1 paper, 2025). Solid crystalline precipitates in the biliary tract, usually formed in the gallbladder, resulting in the condition of cholelithiasis. "However, when pancreatic duct obstruction or direct damage to pancreatic acinar cells occurs due to factors such as gallstones, alcohol, drugs, or metabolic disturbances, lysosomal hydrolase cathepsin B (CTSB) abnormally fuses with zymogen granules." (PMID 40842993, 2025).
gastrointestinal carcinomas (1 paper, 2015). "Overexpression of heparanase-1 and heparanase-2, along with increased heparanase-1 and cathepsin B activity in plasma, is associated with the diagnosis of gastrointestinal carcinoma." (PMID 25351637, 2015). "Heparanase and cathepsin B analysis may develop into a safer and less invasive novel diagnostic tool for gastrointestinal carcinomas." (PMID 25351637, 2015). "The analysis on heparanase isoforms and cathepsin B in the plasma of patients with gastrointestinal carcinomas that was proposed in the present study revealed that this is a potential new diagnostic tool." (PMID 25351637, 2015). "The aim of this study was to analyze heparanase isoform expression and cathepsin B activity in plasma samples from patients with gastrointestinal carcinomas, compared with healthy individuals (control group)." (PMID 25351637, 2015). "The aim of this study was to evaluate isoforms of heparanase and cathepsin B in plasma samples from patients with primary gastrointestinal carcinoma, in comparison with healthy individuals." (PMID 25351637, 2015). "Cathepsin B enzymatic activity was higher in the plasma samples of patients with gastrointestinal carcinomas than in the control group." (PMID 25351637, 2015).
genitourinary cancers (1 paper, 2022). "Our data suggested that CTSB/L are overexpressed in aerodigestive and genitourinary cancers when compared with that in matched normal tissues, and their expressions were closely related to the prognosis of some cancer types." (PMID 35155389, 2022).
gliosarcoma (1 paper, 2015). A rare histological variant of glioblastoma (WHO grade IV) characterized by a biphasic tissue pattern with alternating areas displaying glial and mesenchymal differentiation (WHO). "This syngeneic orthotopic tumor model is derived from 9L rat gliosarcoma cells, which express active cathepsin B. Because hydrolysis of poly-L-glutamate catalyzed by cathepsin B releases exchangeable amine protons, the CEST contrast will increase upon enzymatic action." (PMID 26157794, 2015).
gnathostomiasis (1 paper, 2022). "Our data also show that cathepsin B may be another good diagnostic candidate for human gnathostomiasis." (PMID 35484317, 2022). "The data suggest that collagenase 3, cathepsin B, glutathione S-transferase 1, cuticle collagen 14, major antigen, zinc metalloproteinase nas-4, major egg antigen, peroxiredoxin, and superoxide dismutase [Cu–Zn] may be good candidates for novel human gnathostomiasis diagnostic assays." (PMID 35484317, 2022).
gynecological cancer (1 paper, 2022). "Although the expressions of CTSB/L in aerodigestive and genitourinary tract cancers are not as high as found in thyroid and gynecological cancers, there remains a high risk of SARS-CoV-2 infection in these cancers." (PMID 35155389, 2022). "Importantly, CTSB/L had significantly higher expressions in thyroid and gynecological cancer than any other cancer type." (PMID 35155389, 2022).
hepatitis C (1 paper, 2021). "In the present study, we analyzed whether polymorphisms in inflammasomes genes IL1B rs16944, IL18 rs187238, NLRP3 rs10754558, CARD8 rs2009373, CTSB rs1692816 and AIM2 rs1103577 are associated with susceptibility to HCV infection and liver fibrosis in hepatitis C patients in the Amazon population." (PMID 34161370, 2021). "Similarly, heterozygote carriers for CTSB rs1692816 and AIM2 rs1103577 (padj = 0.008) or for IL18 rs187238 and NLRP3 rs10754558 (padj = 0.005), have less chances to the development of hepatitis C." (PMID 34161370, 2021).
hereditary pancreatitis (1 paper, 2018). "However, both isoforms were readily activated by enteropeptidase and cathepsin B. We conclude that ferret trypsinogens do not autoactivate as their human paralogs and cannot be used to model the effects of trypsinogen mutations associated with human hereditary pancreatitis." (PMID 30305676, 2018).
Hodgkin′s lymphoma (1 paper, 2020). "Cathepsin B-specific module, for example, has been successfully implemented for this role, which led to the development of FDA approved therapies; for example, Brentuximab vedotin (Adcetris®) for CD30-positive relapsed or refractory Hodgkin′s lymphoma." (PMID 32041276, 2020).
hyperuricemia (1 paper, 2025). An abnormally high level of uric acid. "First, our research focused exclusively on male mice and male patients, given the higher prevalence of hyperuricemia in males; however, potential sex-specific differences in CTSB expression and uric acid metabolism require further investigation." (PMID 40457023, 2025).
ileum cancer (1 paper, 2017). "Other protein-encoding genes (FGL2, CTSB, TPP1, SLCO2B1, NARF and JTB) have disease related functions, such as viral hepatitis and ileum cancer." (PMID 28401895, 2017).
ileus (1 paper, 2015). Decrease in peristalsis in the absence of a mechanical bowel obstruction. "In the traumatic post-operative ileus surgery model, deleting the cathepsin B gene results in significantly less ECM breakdown and collagen-type IV loss than occurs in wt animals in that model." (PMID 26388830, 2015).
inclusion body myositis (1 paper, 2025). A slowly progressive degenerative inflammatory disorder of skeletal muscles characterized by late onset weakness of specific muscles and distinctive histopathological features. "In addition, using a cellular model of sporadic-inclusion-body myositis, cathepsin B regulation has been shown to be involved in the progression of muscle disease." (PMID 40427636, 2025).
injury (1 paper, 2025). Damage inflicted on the body as the direct or indirect result of an external force, with or without disruption of structural continuity. "PFD + LIR treatment significantly reduced CTSB expression, consistent with prior findings that CTSB release activates NLRP3 following liver injury." (PMID 41413484, 2025).
intervertebral disc degeneration (1 paper, 2019). "Interleukin 6 and cathepsin B seem to be related with physiopathology of intervertebral disc degeneration, since the levels of both were higher in discs of patients with intervertebral disc degeneration." (PMID 31482941, 2019). "Data confirm that interleukin 6 and cathepsin B are possible related to the physiopathology of intervertebral disc degeneration, however they do not represent a biomarker in serum." (PMID 31482941, 2019).
intestinal schistosomiasis (1 paper, 2020). An intestinal infection that is caused by Schistosoma japonicum. "S. mansoni Cathepsin B (SmCB) is a well-documented vaccine target for intestinal schistosomiasis." (PMID 33304354, 2020).
keloid (1 paper, 2022). An irregularly shaped, elevated mark on the skin caused by deposits of excessive amounts of collagen during wound healing. "Furthermore, two modules of macrophages (Module2: highly expresses RNASE1, C1QA, CD163, CD14, C1QC, FCGRT, and MS4A7; Module10: highly expresses APOC1, CTSB, CTSL, and TYROBP), which exhibited the characteristics of TAMs, increased significantly in keloid." (PMID 35990663, 2022).
kidney injury (1 paper, 2022). Trauma to the kidney. "In those kidney injury models, downregulation or inhibition of CTSB activity ameliorated the severity of AKI demonstrated the role of lysosomes or CTSB as a common pathway in S-AKI pathophysiology." (PMID 36713420, 2022).
laryngeal carcinoma (1 paper, 2023). Carcinoma that arises from the laryngeal epithelium. "In addition, overexpression of stefin A can inhibit the migration, invasion, and proliferation of laryngeal cancer cells via CTSB downregulation." (PMID 37576397, 2023).
legionella infection (1 paper, 2021). "CTSB has been shown to interact with bacterial proteins during legionella infection of macrophages, containing infection through programmed cell death." (PMID 34442377, 2021).
leptospirosis (1 paper, 2022). A contagious bacterial infection caused by spirochetes of the genus Leptospira. "Then, a cascade of inflammation is activated in the renal tubular cells, as leptospirosis induces interleukin (IL)-1β and IL-18 secretion from human macrophage cells through reactive oxygen species and cathepsin B mediated-NLRP3 inflammasome activation." (PMID 35203344, 2022).
Lewy body dementia (1 paper, 2022). A progressive form of dementia characterized by the presence of protein deposits called Lewy bodies in the midbrain and cerebral cortex, and loss of cholinergic and dopaminergic neurons. "The CTSB variant rs1293298 was also identified as the modifier of risk and age of onset in GBA associated PD and Lewy body dementia." (PMID 35806091, 2022).
liver cirrhosis (1 paper, 2016). "These factors include CTSB expression, gender, age, tumor size, Serum HBsAg, serum AFP, tumor size, liver cirrhosis, stage, tumor recurrence, and tumor differentiation." (PMID 26896959, 2016). "Besides CTSB expression level, tumor size, serum AFP, liver cirrhosis, stage, tumor recurrence, and tumor differentiation were also significantly correlated with overall survival in univariate analysis." (PMID 26896959, 2016).
male infertility (1 paper, 2022). The inability of the male to effect fertilization of an ovum after a specified period of unprotected intercourse. "Our findings further elucidate the role of CTSB in regulating autophagy and apoptosis and can be used to inspire prospective strategies for male infertility therapy." (PMID 36518274, 2022).
monocytic leukemia (1 paper, 2013). "In the case of THP-1 (humanacute monocytic leukemia cell line), 1,000 nm silica has been shown to firstgenerate ROS, leading to subsequent rupture of the endosomes and cathepsin B releaseto cytosol." (PMID 23874646, 2013).
neurologic autoimmune diseases (1 paper, 2015). "Changes in cathepsin B activity have also been implicated in numerous neurologic autoimmune diseases." (PMID 26075905, 2015).
neuronal ceroid lipofuscinosis (1 paper, 2023). "Genes for lysosomal proteases are increased, including CTSB, CTSC and CTSD, which is mutated in neuronal ceroid lipofuscinosis (NCL) type 10." (PMID 37747131, 2023).
neuropathy (1 paper, 2023). A disorder affecting the nervous system that manifests with pain, tingling, numbness, and/or muscle weakness. "However, when AGEs accumulate in the hippocampus and cause neuropathy, cathepsin B and E levels increase in microglia accumulated in the hippocampus prior to neuropathy." (PMID 37511915, 2023).
Peritoneal Fibrosis (1 paper, 2019). Disorder characterized by a wide range of structural changes in PERITONEUM, resulting from fibrogenic or inflammatory processes. "We also examined the effects of cathepsin B on the secretion of MMPs, TIMPs, and uPA in in vitro cultured HPMCs and on peritoneal fibrosis in a chlorhexidine-treated mouse model." (PMID 31815017, 2019). "Further studies are needed to confirm the effect of cathepsin B on the peritoneum and to explore the possibility of cathepsin B as a therapeutic target in PD patients with peritoneal fibrosis." (PMID 31815017, 2019). "The results of our in vivo study showing that cathepsin B decreased the thickness of the submesothelial layer suggest that cathepsin B, which is secreted by HPMCs after high glucose stimulation, might reduce peritoneal fibrosis in PD patients." (PMID 31815017, 2019). "The potentially beneficial effect of cathepsin B in the peritoneal fibrosis of our study suggests that its induction by high glucose and LPS might represent a negative feedback effect during the process of fibrosis." (PMID 31815017, 2019). "In the current study, cathepsin B ameliorated the thickening of the submesothelial layer in a peritoneal fibrosis mouse model and its inhibitor, cystatin C, attenuated the effect of cathepsin B, suggesting a possible role for cathepsin B in reducing peritoneal fibrosis in patients receiving PD." (PMID 31815017, 2019). "We aimed to investigate the role of cathepsin B in peritoneal fibrosis in PD patients." (PMID 31815017, 2019). "Further studies are needed to study the role of cathepsin B in peritoneal fibrosis in PD patients." (PMID 31815017, 2019). "Evidence for the effect of cathepsin B on peritoneal fibrosis is currently lacking." (PMID 31815017, 2019). "However, the roles of cathepsin B and cystatin C in peritoneal fibrosis have not been investigated." (PMID 31815017, 2019).
pineoblastoma (1 paper, 2020). Pineoblastoma is a rare, malignant type of supratentorial primitive neuroectodermal tumor (sPNET), found mainly in children (less than 10% of cases are reported in adults), and located in the pineal region of the brain but that can metastasize along the neuroaxis. "Nortriptyline disrupts the lysosome, leading to accumulation of non-functional autophagosome, cathepsin B release and pineoblastoma cell death." (PMID 32286280, 2020).
placental abruption (1 paper, 2016). Vaginal bleeding preceding the 20th week of gestation. "As the correct proportion of cathepsin B and cystatin C is crucial for an uncomplicated implantation and further placentation, an important role of these enzymes in placental abruption may be considered." (PMID 26904684, 2016).
pneumococcal meningitis (1 paper, 2015). An acute purulent infection of the meninges and subarachnoid space caused by Streptococcus pneumoniae, most prevalent in children and adults over the age of 60. "In addition, it has been shown that NLRP3 inflammasome plays a central role in brain injury through ATP-dependent lysosomal cathepsin B release in pneumococcal meningitis." (PMID 26683708, 2015).
polymyositis (1 paper, 2025). A rare idiopathic inflammatory myopathy characterized by symmetric proximal muscle weakness and elevated muscle enzymes. "Interestingly, the administration of the specific cathepsin B inhibitor CA-074Me attenuates apoptosis of myocytes and reduces both inflammation and fibrosis in a guinea pig model of polymyositis." (PMID 40427636, 2025).
progressive myoclonus epilepsy (1 paper, 2014). A rare group of disorders characterized by the development of myoclonic and tonic-clonic epileptic seizures associated with progressive degeneration of the nervous system. "It has been reported that dysregulation of cystatin B-cathepsin B signaling may serve as a critical mechanism coupling oxidative stress to neuronal degeneration in progressive myoclonus epilepsy." (PMID 25470616, 2014).
Pseudoxanthoma elasticum (1 paper, 2022). "The suppressive role of CTSB on the expression of XYLT1 was further validated by the quantification of CTSB expression in fibroblasts from patients with the inflammation-associated disease Pseudoxanthoma elasticum." (PMID 35740472, 2022).
psoriasis plaques (1 paper, 2023). "Cathepsin B is a protease with pro-inflammatory functions that is highly expressed in psoriasis plaques." (PMID 37681909, 2023).
rectal cancer (1 paper, 2024). A primary or metastatic malignant neoplasm that affects the rectum. "Computational analysis from both differential expression and survival plots highlighted CTSB and CPNE1, and therefore, these were implicated in colon and rectal cancers." (PMID 38544823, 2024).
renal hypertension (1 paper, 2024). Hypertension caused by the kidney's hormonal response to narrowing or occlusion of the renal arteries. "Furthermore, in mice with renal hypertension induced by NPHS2 gene knockout, western blot and immunohistochemical staining analyses revealed a notable increase in CTSB expression in podocytes, glomeruli and intercalated cells." (PMID 39248527, 2024).
Renal insufficiency (1 paper, 2022). A reduction in the level of performance of the kidneys in areas of function comprising the concentration of urine, removal of wastes, the maintenance of electrolyte balance, homeostasis of blood pressure, and calcium metabolism. "Hydroxychloroquine (HCQ) reduces renal insufficiency by downregulating NLRP3 inflammasomes activation mediated by CTSB and CTSL." (PMID 36209090, 2022).
rheumatic diseases (1 paper, 2021). "Moreover, since DCN, CTSB and MMP2 also promote the inflammatory process in OA, reduction mediated by VIP again corroborates its well-known anti-inflammatory role in rheumatic diseases." (PMID 34208590, 2021).
scrapie (1 paper, 2025). A fatal disease of the nervous system in sheep and goats, characterized by pruritus, debility, and locomotor incoordination. "Similar to the western blotting results in ME7 scrapie-infected mice, the expression levels of CD10, cathepsin B, cathepsin D, and MMP9-40 kDa were upregulated in sporadic CJD patients." (PMID 40302732, 2025). "We observed an abnormal accumulation of proteolytic stress-related proteins, including CD10, cathepsin B, cathepsin D, and matrix metalloproteinase 9 (MMP9), in the brains of ME7 scrapie-infected mice and sporadic CJD patients." (PMID 40302732, 2025). "In conclusion, we identified abnormal accumulation of proteolytic stress-related proteins, including CD10, cathepsin B, cathepsin D, and MMP9, in the brains of ME7 scrapie-infected mice and sporadic CJD patients." (PMID 40302732, 2025). "In detail, the expression levels of CD10, cathepsin B, cathepsin D, and MMP9-40 kDa were upregulated in ME7 scrapie-infected mice." (PMID 40302732, 2025). "Notably, proteolytic stress-related proteins, including CD10, cathepsin B, cathepsin D, and matrix metalloproteinase 9 (MMP9), showed altered expression patterns in ME7 scrapie-infected mice compared to matched controls." (PMID 40302732, 2025). "Notably, proteolytic stress-related proteins, including CD10, cathepsin B, cathepsin D, and MMP9, were also upregulated in the cerebral cortex and caudate putamen of ME7 scrapie-infected mice compared to matched controls." (PMID 40302732, 2025).
serous ovarian carcinomas (1 paper, 2014). "It has been reported that CSTB, derived from serous ovarian carcinomas, strongly inhibits papain and cathepsin L and moderately inhibits cathepsin B." (PMID 24452274, 2014).
stomach diseases (1 paper, 2022). "Furthermore, GPR35 in CTSB+ and CD68 + macrophage for EGC had a notable high expression level when compared to those of other stomach diseases." (PMID 36333291, 2022).
subarachnoid hemorrhage (1 paper, 2015). A serious neurological disorder characterized by intracranial hemorrhage into the subarachnoid space. "In a subarachnoid hemorrhage model, cathepsin B protein increased about 3.5-fold at 2 and 3 days after hemorrhage induction relative to controls." (PMID 26388830, 2015).
systemic sclerosis (1 paper, 2012). A chronic disorder, possibly autoimmune, marked by excessive production of collagen which results in hardening and thickening of body tissues. "Cathepsin B levels in dermal vasculature in normal and systemic sclerosis skin." (PMID 22384200, 2012).